MPV17L2 (MPV17 mitochondrial inner membrane protein like 2)
Description:
Required for the assembly and stability of the mitochondrial ribosome. Is a positive regulator of mitochondrial protein synthesis.
Synonyms: FKSG24; MGC12972
Tractability: Antibody: UniProt predicts a signal peptide or a membrane-spanning region.
Gene: Protein-coding gene on chromosome 19 (18,193,218 to 18,196,948, forward strand). Ensembl gene ENSG00000254858.
Subcellular location: Membrane; Mitochondrion inner membrane
Gene Ontology:
Molecular function: mitochondrial large ribosomal subunit binding
Biological process: mitochondrial ribosome assembly; positive regulation of mitochondrial translation
Cellular component: mitochondrial inner membrane; mitochondrion; membrane
Genetic constraint (gnomAD): Loss-of-function variants: 28 observed, 24.98 expected, observed/expected ratio (o/e) 1.12, 90% interval 0.83 to 1.53. The upper end of that interval is the gene's LOEUF score, 1.53, which puts it in group 6 of 6, group 1 being the genes least tolerant of losing a copy. Missense variants: 271 observed, 245.57 expected, observed/expected ratio (o/e) 1.1, 90% interval 1 to 1.22. Synonymous variants: 130 observed, 113.5 expected, observed/expected ratio (o/e) 1.15, 90% interval 0.99 to 1.33.
Homologues: Orthologues: chimpanzee MPV17L2 (100% identical), macaque MPV17L2 (99% identical), pig MPV17L2 (88% identical), dog MPV17L2 (81% identical), mouse Mpv17l2 (76% identical), guinea pig MPV17L2 (75% identical), rat Mpv17l2 (75% identical), Drosophila melanogaster CG5906 (7% identical), Drosophila melanogaster CG1662 (5% identical), zebrafish mpv17l2 (5% identical), tropical clawed frog mpv17l2 (4% identical), Caenorhabditis elegans ZK470.1 (1% identical). Paralogues in human: PXMP2 (27% identical), MPV17 (26% identical), MPV17L (22% identical).
Diseases named in the same sentence as MPV17L2 in open-access papers:
MPV17L2 is named in the same sentence as 3 diseases in open-access papers, as found by Europe PMC text mining. Sharing a sentence is not in itself a finding about the gene and the disease. The quoted sentences say what the papers report.
amyotrophic lateral sclerosis (1 paper, 2021). Amyotrophic lateral sclerosis (ALS) is a neurodegenerative disease characterized by progressive muscular paralysis reflecting degeneration of motor neurons in the primary motor cortex, corticospinal tracts, brainstem and spinal cord. "Moreover, we identified Wald ratio effects between four genes (IQCB, TTC34, MPV17L2 and SLC30A7) and multiple sclerosis risk, and effects between two genes (SCFD1, G2E3) and amyotrophic lateral sclerosis risk." (PMID 33417599, 2021).
MPV17L2 also shares sentences with these, for which no sentence is quoted: autism (1 paper); multiple sclerosis (1).